EZH2 (enhancer of zeste 2 polycomb repressive complex 2 subunit)
Diseases named in the same sentence as EZH2 in open-access papers (continued):
Sharing a sentence is not in itself a finding about the gene and the disease.
tumor (continued). "Imbalances between both complexes can be due to overexpression of EZH2 in undifferentiated cancers, but most commonly occur in cancers by mutations of members of the SWI/SNF complex, such as ARID1A and SMARCA4 that together with SMARCA2 is the ATPase subunit of this tumor-suppressing complex." (PMID 33230143, 2020). "Given that profound epigenetic evolution may occur in the long journey of circulating tumor cells (CTCs) to distant organs, we hypothesized that EZH2 endowed tumor cells with enhanced malignant features (e.g., stemness and motility) during hepatic metastasis in UM." (PMID 32127003, 2020). "To determine whether EZH2 inhibition in vivo affects tumour growth, we treated two CRC patient-derived xenograft models with vehicle control or UNC1999 at 300 mg/kg for 11-day cycles of 9 consecutive days of treatment followed by 2 days of break, which was well tolerated by the mice." (PMID 30926792, 2019). "However, as demonstrated in other studies, the EZH2 may have tumor suppressive and oncogenic functions in MDS and in AML." (PMID 31886200, 2019). "EZH2 was found to be overexpressed in MDS tumor cells associated with methylation of tumor suppressor gene cyclin dependent kinase inhibitor 2B (p15INK4B) compared with tumor cells that p15INK4B is not methylated." (PMID 31886200, 2019). "Subsequently, we used Transwell assay to test whether EZH2 regulates tumor cell migration." (PMID 31718595, 2019). "In the present study, consistent with ES dependence on EZH2 as a consequence of INI1 deficiency, we observed significant antitumor activity of EPZ-011989 in our PDX model, although with different kinetics of tumor growth inhibition compared to chemotherapeutics." (PMID 31331120, 2019). "Next, we used a Matrigel-based 3D culture system, which can provide better microenvironment for functional assays, to further examine whether tumor cells expressing EZH2T416D undergo the basal-to-luminal phenotypic changes when their EZH2 activities are blocked." (PMID 31704972, 2019). "Tumor nodules of shNFATc2 transfectants removed from SCID mice were negative for EZH2, suggesting that loss of expression of both NFATc2 and EZH2 could contribute to the observed strong anti-tumor effect." (PMID 30710146, 2019). "In SMARCB1/SNF5-deficient tumor cells, EZH2 inhibitor treatment can increase p16INK4a expression by lowering the level of tri-methylated H3K27 in the p16INK4a gene region, which demonstrates that EZH2 epigenetically silences the expression of p16INK4a by catalyzing H3K27 tri-methylation." (PMID 31590683, 2019). "Moreover, flow cytometric results revealed that ALDH1 activity was decreased in resistant cells pretreated with EPZ011989 compared to untreated resistant cells suggesting that EZH2 inhibition activity can reduce the presence of the CSC-like subpopulation in the tumor." (PMID 30683135, 2019). "According to recent studies, lncRNA MALAT1 is capable of upregulation of well-established epi-miRNA (subclass of tumor-suppressor miRNA with an ability to revert epigenetic aberrations) called miR-29b characterized by inverse correlation with enhancer of zeste homolog 2 (EZH2) mRNA expression." (PMID 30682861, 2019). "Besides its functional role for cell cycle regulation, EZH2 is also involved in metastasis by modulating tumor angiogenesis and the epithelial-to-mesenchymal transition, a process by which disseminating tumor cells acquire mesenchymal characteristics to migrate through the extracellular matrix." (PMID 31317325, 2019).
tumor (continued). "As EZH2 and H3K27me3 expressions lead to transcriptional repression of tumor suppressor genes, including E-cadherin, and promote tumor progression, it is anticipated that inhibition of EZH2 and H3K27me3 would enhance the sensitivity of tumor cells to cisplatin." (PMID 31043583, 2019). "Finally, we recommend that epigenetic therapies with EZH2 inhibitors should be carefully evaluated for each specific tumor type, since alterations in cell differentiation might lead to unfavorable results." (PMID 31317325, 2019). "In addition, EZH2 seems to play a crucial role in favoring tumor angiogenesis." (PMID 29642503, 2018). "Notably, repressing CREB inhibits the CREB/EZH2 axis, tumor growth, NED, and angiogenesis in vivo." (PMID 30287808, 2018). "Therefore, enforced expression of Gfi1 promotes secondary G3 MB formation mimicking the effects of the absence of Ezh2, whereas the lack of Gfi1contrasted the effects of Ezh2 inactivation, together providing at least a partial rationale for Ezh2-mediated tumor suppression." (PMID 30510924, 2018). "Inhibition of EZH2 expression or activity in hematopoietic stem and progenitor cells (HSPCs) gives rise to increased NK precursors and mature progeny, which displays enhanced cytotoxicity against tumor cells with up-regulation of IL-15R (CD122) and the NKG2D-activating receptor." (PMID 29556394, 2018). "Taken together, EZH2 may participate in tumor invasion/metastasis." (PMID 29642503, 2018). "If this finding is corroborated in tumor cell models it might be highly pertinent to the ability of Smurf2 to interfere with carcinogenesis, as EZH2 was documented as a pro-oncogenic factor involved in neoplastic transformation, cancer cell stemness, metastases and immune evasion." (PMID 30116722, 2018). "The enhancer of zeste homolog 2 (EZH2) is a critical member of the Polycomb Repressive Complex 2 (PRC2) that regulates histone methylation mainly via lysine 27 at histone H3 (H3K27), a modification associated to transcriptional silencing that is found upregulated in many tumor types." (PMID 29888169, 2018). "In addition to the expression and function of EZH2 in cancer cells, recent studies also revealed that EZH2 might have critical roles in tumor immunity." (PMID 29556394, 2018). "Thus, our data suggest that EZH2 expression in tumour cells might contribute in shaping the nature of immune infiltration also in the setting of MpMs, as already proved in other solid tumours." (PMID 30510965, 2018). "Moreover, systemic nanoparticle delivery of siRNAs or antagomirs targeting tumor-assisting non-coding RNAs (such as EZH2, HOTAIR, and miR-298) into ovarian TECs may provide an additional option for combinatorial blocking of EOC tumor growth and angiogenesis." (PMID 30200265, 2018). "Therefore, EZH2 inhibition in T cells may suppress survival, expansion and effect of tumor-specific effectors T cell to inhibit anti-tumor immunity." (PMID 29556394, 2018). "In addition, EZH2 is demonstrated to promote tumor cell invasion." (PMID 29556394, 2018). "Interestingly, small-molecule EZH2 inhibitors abolish the growth of DPIG tumor cells, suggesting that EZH2 inhibition could represent a strategy for the treatment of DPIGs." (PMID 30279357, 2018). "Furthermore, xenograft study also substantiated that stable overexpression miR‐144‐3p induced by miR‐144‐3p mimics could decrease the expression of EZH2, suppressing tumor growth." (PMID 30280514, 2018). "However, the mechanism by which EZH2 promotes tumor invasion remains elusive." (PMID 28620234, 2017). "Whether H3K27me3 and DNA methylation cooperate to silence miRNAs with tumor suppressor functions such as miR-125a and miR-320c in MM remains to be further elucidated, and if so, combining EZH2 and DNA methylation inhibitors could prove beneficial to target the malignant plasma cell." (PMID 28052011, 2017). "Thus, EZH2 expression and function should be investigated in each individual type of tumor." (PMID 28415635, 2017).
tumor (continued). "This positive staining may be associated with the fact that the EZH2 protein participates in embryo development: the EZH2 knockdown was shown to be embryo-lethal in mice; the knockdown of EZH2 in cancer cells resulted in diminished tumor growth and reduced metastases in vivo." (PMID 28642877, 2017). "The mutations in this tumor included 3 predicted high impact mutations in MTOR a regulator of stress response, OGT a glycosyltransferase that modifies a broad range of targets including H2B, AKT1, EZH2, PFKL, KMT2E/MLL5, MAPT/TAU and HCFC1, and FAM129B a negative regulator of apoptosis." (PMID 28415633, 2017). "Thus, we investigated whether EZH2 activates downstream oncogenic networks to promote EC progression by downregulating potential tumor suppressor miRNAs." (PMID 28088786, 2017). "However, downregulation of EZH2 made cells enter a period of stasis in G1 to inhibit the proliferation of cancer cell lines, which may reverse the condition of tumor and prolong the overall survival of patients." (PMID 27706111, 2016). "However, one should keep in mind that the MEG3 tumor suppressive function is also EZH2-mediated." (PMID 26992233, 2016). "Targeting of EZH2, a potential therapeutic strategy, may induce apoptosis and tumor cell death." (PMID 27706111, 2016). "Moreover, EZH2 activity might have significant impact on immune-mediated tumor distraction in response to immunotherapy with checkpoint inhibitors." (PMID 27793053, 2016). "Moreover, high expression levels of EZH2 detected in primary tumor tissue could be exploited to improve quality of tumor stage classification." (PMID 27471434, 2016). "We hypothesize that the tumor-specific epigenetic enzyme EZH2 is selectively expressed in IM." (PMID 27842164, 2016). "Finally, we tested whether LINC00152 interacts with EZH2 to affect tumor cell cycle progression by silencing gene expression." (PMID 26799422, 2016). "Notably, EZH2 appears to be not only a promising tumor biomarker but may itself contribute to tumor progression, similar to an oncogene." (PMID 26868841, 2016). "However, recent work revealed that EZH2 might have a novel and important involvement in cancer via a mechanism that alters the immunogenicity of the tumor microenvironment." (PMID 27793053, 2016). "Therefore, it would be interesting to target redundant epigenetic repressive marks (such as DNA methylation, H3K9 di- and tri-methylation), or the absence of activation marks, such as H3K4 tri-methylation or H3K27 acetylation (H3K27ac), to sensitize tumor cells to EZH2 inhibition." (PMID 26497210, 2016). "In vitro, the inhibition of EZH2, achieved through the prolonged exposure of human K-RAS-mutant NSCLC cells to an inhibitor of EZH2 catalytic activity (GSK126), resulted in a strong increase of inflammatory genes (i.e., IL-6) associated with microenvironment-regulated tumor progression." (PMID 27239242, 2016). "Moreover, we unveil a new functional connection between miR-101 and EZH2 in this tumor context." (PMID 26251675, 2015). "Therefore, on one hand, these results demonstrate that miR-101 is able to regulate EZH2 levels also in the eRMS tumor cell context and, on the other hand, they shed light on the molecular mechanisms by which EZH2 could be up-regulated in eRMS." (PMID 26251675, 2015). "Moreover, suppression of EZH2 markedly inhibited tumor growth and lung metastasis in vivo." (PMID 26265454, 2015). "Notably, EZH2 appears to be not only a potential tumor biomarker but may itself contribute to the deregulation of tumor cells similar to an oncogene." (PMID 26265454, 2015). "In addition, this result suggests that decreased levels of EZH2 relative to proliferation might accelerate tumor development." (PMID 26637281, 2015). "Therefore, the biological function of EZH2 could be related to other tumor suppressor genes or EZH2′s own effect." (PMID 26265454, 2015).
tumor (continued). "Thus, our study revealed that CHD5 is a novel direct target of EZH2, and may be part of a tumor suppressor network that is suppressed by EZH2." (PMID 26517514, 2015). "Thus, whether elevated expression of EZH2 in carcinomas actively contributes to tumor progression or is simply a consequence of malignant evolution remains an open question." (PMID 26637281, 2015). "Despite our large sample size, in our study we were not able to show a significant association between EZH2 rates and clinical tumor behavior, especially size and invasiveness, possibly because of the low proportion of tumor samples with a high proliferative capacity." (PMID 26593398, 2015). "We demonstrate that knockdown of EZH2 by RNA silencing is sufficient to induce the up-regulation of the endogenous levels of miR-101 in eRMS cells, thus suggesting that EZH2 might repress miR-101 in this tumor type, as reported for other cancers." (PMID 26251675, 2015). "Thus, EZH2 might inhibit the expression of tumor suppression genes in response to trimethylation of H3K27 in the PTEN promoter region and augment the self-renewal capability of AML cells." (PMID 25955299, 2015). "EZH2 might be responsible, at least in part, for the tumor resistance to radiotherapy." (PMID 25159232, 2014). "The group found that loss of miR-26a led to upregulation of EZH2 in TMPRSS2:ERG negative tumours." (PMID 25496077, 2014). "To further investigate whether this upregulation of p16INK4a was reflecting changes in the transcription levels of known regulators of this tumor suppressor, such as Bmi1 15,25, Ezh1 26, Ezh2 27,28, and Suz12 29, we analyzed the expression of these genes by qPCR." (PMID 24307508, 2014). "Thus, NSC745885 had potent anti-tumor effects and down-regulated EZH2 in vivo." (PMID 25431950, 2014). "In various tumor types, especially in those miR-26a functions as a tumor suppressor, miR-26a was demonstrated to inhibit proliferation and colony formation through down-regulation of the histone-lysine N-methyltransferase, EZH2, a global regulator of gene expression." (PMID 23750239, 2013). "EZH2 disturbance could be a pivotal driver of tumor development." (PMID 24312307, 2013). "Reducing EZH2 expression using siRNA or treatment of a small-molecule-S-adenosylhomocysteine hydrolase inhibitor 3-deazaneplanocin (DZNep) that inhibits methyltransferases and induces degradation of EZH2 was shown to result in cell growth inhibition and reduced tumour formation in various cancers." (PMID 22187039, 2012). "Considering that the expression and function of miRNAs may vary in different types of tumors, here we set out to investigate whether these miRNAs (miR-26a, miR-98, miR-101, miR-124, miR-138 and miR214) regulate tumor metastasis via altering EZH2 expression in human ESCC." (PMID 22867052, 2012). "Finally, we will describe cancer therapies that target EZH2 or its downstream cascades, which could potentially reverse the oncogenic and stemness properties of the tumour cells to suppress cancer progression and recurrence." (PMID 22187039, 2012). "Additionally, shRNA interference of EZH2 leads to poor TSC tumor formation in vivo." (PMID 24212632, 2011). "Moreover, the recent observation that EZH2 may act as a tumor suppressor in certain hematologic disorders suggests that EZH2 inhibition could even promote tumorigenesis, in some tissues." (PMID 21765901, 2011). "The important caveat with these data is that the expression of DNMTs and EZH2 correlates with cell proliferation rate; therefore a high level of expression might be a consequence of the proportion of cells proliferating in tumours and/or chronically inflamed tissue." (PMID 20724161, 2010). "Indeed, we found that EZH2 expression progressively increases with pediatric tumor grade." (PMID 20920292, 2010). "However, in vivo experiments should demonstrate whether targeting EZH2 inhibits all tumor-initiating potential." (PMID 19709408, 2009).
tumor (continued). "It remains to be established, however, whether silencing of these genes is responsible for the selective advantage of EZH2 overexpression in BRCA1-deficient tumor cells, and whether these genes include more classical tumor-suppressors or specific differentiation factors." (PMID 19709408, 2009). "First, high BMI1 or EZH2 levels may reflect a different cell of origin for the respective tumours." (PMID 19099573, 2008). "Thus, if a small molecule inhibitor can be identified against EZH2 enzymatic activity or its protein–protein interactions, this may have utility as a viable therapeutic against tumours expressing high levels of EZH2." (PMID 16880794, 2006). "Previous research has demonstrated that EZH2 is aberrantly overexpressed in CRC and functions to suppress ferroptosis in these tumor cells." (PMID 41561226, 2026). "Stabilized FOXA1 promotes expression of cell-cycle genes and proliferation, and dual inhibition of EZH2 and USP7 markedly suppresses tumor growth in FOXA1-high PCs in vitro and in vivo." (PMID 41601922, 2026). "Secondly, While our in vitro and in vivo findings support the tumor-promoting roles of OLFML2A and EZH2 in TNBC progression, future large-scale clinical studies are needed to definitively correlate their expression with patient outcomes." (PMID 41607539, 2026). "In PC, canonically, EZH2-mediated histone H3K27 trimethylation represses and silences developmental and tumor suppressor genes, driving proliferation, invasion, angiogenesis, and therapy resistance." (PMID 41601922, 2026). "EZH2-driven H3K27me3 silences these microRNAs, thereby stabilizing NSD2 expression and elevating H3K36me2, which promotes tumor growth and metastasis." (PMID 41601922, 2026). "On the other hand, depletion of DE Tfh cells via Ezh2 gene deletion, inhibition of EZH2 (using FDA-approved drug, tazemetostat), or anti-CXCR6 mAb led to tumor regression." (PMID 41695367, 2026). "EZH2, the catalytic component of the polycomb repressive complex 2 (PRC2), mediates histone H3K27 trimethylation, silencing tumor suppressor genes and promoting malignant transformation." (PMID 42257802, 2026). "We also clarify potential mechanisms that operate for both EZH2 monotherapy and combination therapy in TCL, revealing the activation of STAT1 as one of the tumor-suppressive pathways contributing to the anti-tumor effects." (PMID 40659662, 2025). "In addition to its role in restoring MHC-I expression, EZH2 inhibitors may have further tumor-suppressive effects on SCLC through broader transcriptional reprogramming, which includes the hyperactivation of ribosome biogenesis, epithelial-mesenchymal transition, and MYC targets." (PMID 41353272, 2025). "As a tumor suppressor, OAS2 is related to gefitinib resistance that DUXAP10 recruits EZH2 epigenetically silencing OAS2." (PMID 40701777, 2025). "In summary, our data elucidate the role of squamocin in the degradation of both EZH2 and MYC across multiple tumor models." (PMID 39823459, 2025). "HOTAIR interacts with EZH2 to recruit the PRC2 complex, which catalyzes H3K27me3, thereby repressing the expression of tumor suppressor genes." (PMID 41353219, 2025). "The mechanism underlying this involves ANLN inhibition of miR-218-5p expression through regulation of the histone methyltransferase EZH2, thereby disinhibiting the downstream target gene LASP1 and promoting tumor cell proliferation." (PMID 41573677, 2025).